DPYSL3 (dihydropyrimidinase like 3)
Diseases named in the same sentence as DPYSL3 in open-access papers (continued):
Sharing a sentence is not in itself a finding about the gene and the disease.
lymph node metastasis (5 papers, 2014 to 2023). "In UTUC, high DPYSL3 expression was associated with advanced-stage (p < 0.001), lymph node metastasis (p < 0.001), high histological grade (p < 0.001), vascular invasion (p < 0.001), perineural invasion (p < 0.001), and a high mitosis rate (p < 0.001)." (PMID 37380971, 2023). "In patients with UBUC, increased expression of DPYSL3 was frequently related to muscle-invasive bladder cancer (MIBC) (p < 0.001), lymph node metastasis (p = 0.012), vascular invasion (p < 0.001), and perineural invasion (p = 0.021)." (PMID 37380971, 2023).
gastric tumors (4 papers, 2016 to 2023). "Previous studies have indicated involvement of DPYSL3 in malignant pancreatic and gastric tumors." (PMID 28651527, 2017).
amyotrophic lateral sclerosis (3 papers, 2014 to 2023). Amyotrophic lateral sclerosis (ALS) is a neurodegenerative disease characterized by progressive muscular paralysis reflecting degeneration of motor neurons in the primary motor cortex, corticospinal tracts, brainstem and spinal cord. "A DPYSL3 missense variant was however reported in association with amyotrophic lateral sclerosis and shown to impair axonal growth." (PMID 36703211, 2023).
autism (3 papers, 2017 to 2025). Persistent deficits in social interaction and communication and interaction as well as a markedly restricted repertoire of activity and interest as well as repetitive patterns of behavior. "Together, the coordinated downregulation of Nrp1, Nrp2, Robo2, and Dpysl3 suggests potential impairment in axon-guidance signaling cascades in autism." (PMID 41150532, 2025).
schizophrenia (3 papers, 2013 to 2020). A major psychotic disorder characterized by abnormalities in the perception or expression of reality. "In another postmortem study of the DLPFC in schizophrenia, miR-132 was observed to be dysregulated and this was supported by the altered expression of its target genes, including DNMT3A, GATA2, and DPYSL3, which are known to be related to the development of the nervous system and schizophrenia." (PMID 32764320, 2020).
colon cancer (2 papers, 2021 to 2023). "We identified seven EMT-related genes (TPM1, LAMC1, POSTN, CCN1, MGP, PCOLCE2, and DPYSL3) with prognostic significance in patients with colon cancer from TCGA and GSE17536 cohorts." (PMID 34180352, 2021).
hepatocellular carcinoma (2 papers, 2020 to 2022). A malignant tumor that arises from hepatocytes. "There was also increased expression of antiangiogenic Dpysl3, which has been observed to inhibit angiogenesis in hepatocellular carcinoma cell lines; and Lif, long known to inhibit Vegf and Fgf stimulation of angiogenesis, was overexpressed." (PMID 34793334, 2022).
bladder tumour (1 paper, 2023). "In addition, high DPYSL3 expression predicted a higher bladder tumour recurrence rate in patients with NMIBC." (PMID 37380971, 2023).
cerebral infarct (1 paper, 2012). "Most of these data seem to suggest acute inhibition of neurogenesis, but the SYPL2 gene (Synaptophysin-like-2) and the neurogenesis marker DPYSL3 (TUC-4) were augmented in the core at 3 d after cerebral infarct, probably reflecting early brain repair responses after damage." (PMID 23284893, 2012).
Diabetes (1 paper, 2020). "We determined the influence of T2D on clinicopathological profile and PM of DPYSL3 and CDK2NA in patients with NBNC-HCC who were divided into two groups: non-diabetes (non-DM; n = 46) and diabetes (DM; n = 47)." (PMID 31980687, 2020).
Down syndrome (1 paper, 2013). "Less is known about Dpysl3 but one postmortem study of patients with Down syndrome noted an upregulation of Dypsl3 and downregulation of Dypsl2, the same pattern we observed after PCP treatment." (PMID 23738220, 2013).
glaucoma (1 paper, 2025). Increased pressure in the eyeball due to obstruction of the outflow of aqueous humor. "While DPYSL3 is involved in glaucoma, dihydropyrimidinase-related protein 5 (DPYSL5) has little information regarding its role in ocular diseases." (PMID 40076480, 2025).
Lewis lung carcinoma (1 paper, 2018). "Stable DPYSL3 knockdown Lewis lung carcinoma (LLC) cells were constructed with a retroviral system." (PMID 29514686, 2018).
liver fibrosis (1 paper, 2025). "Our study directly demonstrates and confirms that DPYSL3 is upregulated in human and mouse liver fibrosis." (PMID 40943308, 2025).
medulloblastoma (1 paper, 2014). A malignant, invasive embryonal neoplasm arising from the cerebellum. "Additional novel findings from our analysis indicate that Group 4 medulloblastoma over-express semaphorin signalling molecules, including DPYSL3 and DPYSL4, which regulate neuronal differentiation and apoptosis in the context of synaptic pruning." (PMID 25412507, 2014). "With this in mind, we assessed key transiently activated neural transcription factors (MATH1, NHLH1), and other temporally activated genes (NEUROD1, NHLH2, NFIB, LPPR4, DPYSL3, NEUROD2) expressed throughout granule neuron differentiation, in the medulloblastoma subgroups." (PMID 25412507, 2014).
Rett syndrome (1 paper, 2021). A severe neurodevelopmental disorder affecting the central nervous system.
urothelial carcinoma (1 paper, 2023). A malignant neoplasm derived from the transitional epithelium of the urinary tract (urinary bladder, ureter, urethra, or renal pelvis). "However, the role of DPYSL3 in affecting the biological behaviour of urothelial carcinoma (UC) is not yet understood." (PMID 37380971, 2023).
viral infections (1 paper, 2025). "Tspan7, a transmembrane glycoprotein functionally involved in many different viral infections was downregulated 10 fold, and neuron development genes Tenm3 and Dpysl3 were down 19.4 fold and 26.8 fold respectively in Prol/CJ− vs Prol/Nl cells." (PMID 40434970, 2025).
cancer (21 papers, 2013 to 2024). A tumor composed of atypical neoplastic, often pleomorphic cells that invade other tissues. "Our study indicates that DPYSL3 acts as a promoter of cancer progression supported by the loss of DPYSL3 reduced cancer migration and EMT." (PMID 32121246, 2020). "In short, higher DPYSL3 levels were associated with poor clinical outcome due to the effects of DPYSL3 on the regulation of cancer migration, invasion and EMT." (PMID 32121246, 2020). "Other important genes in this list downregulated by TOX2-shRNA, such as ITGB7, SLAMF1, CD244, DPYSL3, KRT80 and KRT7, have been implicated in cancer progression or drug resistance." (PMID 37032358, 2023). "Since DPYSL3 actively regulates cancer cell invasion and proliferation, understanding its role in promoting UC cell aggressiveness is essential." (PMID 37380971, 2023). "DPYSL3 is a cell adhesion molecule, and its low expression in PCa cells significantly promotes cancer cell migration and invasion; its concentration is directly proportional to the prognosis of patients." (PMID 37251946, 2023). "Despite this limitation, our study is the first to disclose DPYSL3 in reprogramming energy metabolism in cancer development." (PMID 37380971, 2023). "Conflicting roles of DPYSL3 have been described in different types of cancer, implying that it has a diversity of functions in different malignancies." (PMID 32121246, 2020). "Expression of LSR (A), S100A14 (B) and DPYSL3 (C) in breast, prostate and others (retinal pigment, liver, colon and esophageal) cancer cell lines from QN + SVA normalized integrated data." (PMID 28651527, 2017). "To verify if saRNA-mediated DPYSL3 gene upregulation played a critical role in suppressing cancer cell migration, we co-transfected the saV2-9 saRNA together with a small interfering RNA (siRNA) of DPYSL3 gene in PC-3 cells." (PMID 27014974, 2016). "The saRNA approach by targeting tumor suppressor gene such as DPYSL3 represents a novel direction of cancer gene modulation and drug development." (PMID 27014974, 2016). "GC tissues from tumors with distant metastases (stage IV cancer) showed elevated expression levels of DPYSL3 mRNA." (PMID 25096402, 2014). "We further demonstrated that DPYSL3 regulates cancer cell migration and adhesion in vitro as well as metastasis in vivo, and plays an important role in formation of the adhesion complex." (PMID 24339867, 2013). "We also report detailed functional characterizations of DPYSL3 in relation to cancer cell proliferation, invasion, and metastasis by applying a combined proteomic approach with the aid of multiple reaction monitoring (MRM) technology." (PMID 24339867, 2013). "Previous studies have shown that DPYSL3 has diverse effects on altering cancer cell aggressiveness." (PMID 37380971, 2023). "Univariate analysis for overall survival (OS) showed that tumour multiplicity (multiple), serosal invasion, portal vein invasion, hepatic vein invasion, T3-4 cancer [UICC stage (8th)], history of T2D and PM of DPYSL3 were the significant risk factors for reduced survival." (PMID 31980687, 2020). "We attributed this to differential translational regulation of CDK2NA and DPYSL3 because the prevalence and pattern of PM may be organ and carcinoma specific." (PMID 31980687, 2020). "Characterization of the roles of dihydropyrimidinase-like 3 in relation to cancer cell adhesion and migration in vitro, and metastasis in vivo was performed using a series of functional analyses, including those employing multiple reaction monitoring proteomic analysis." (PMID 24339867, 2013). "In this study, we uncover a previously unknown mechanism by which TTK exerts a significant oncogenic effect by the upregulation of neurotensin (NTS) and dihydropyrimidinase-like 3 (DPYSL3), which promote cancer growth and cancer progression consequently tumor metastasis." (PMID 32121246, 2020).
cancer (continued). "DM was associated with a higher Union for International Cancer Control grade, marginal vascular invasion and tumour cell proliferation irrespective of the duration of T2D as well as higher rates of PM of DPYSL3 than non-DM; however, PM of CDK2NA was similar between both groups." (PMID 31980687, 2020). "The link between DPYSL3 and cancer energy metabolism has never been reported and thus warrants further investigation." (PMID 37380971, 2023).
tumor (19 papers, 2013 to 2024). "In this study, we revealed that DPYSL3 overexpression in UC is associated with tumour aggressiveness." (PMID 37380971, 2023). "Univariate analysis for disease-specific survival (DSS) showed that tumour multiplicity (multiple), serosal invasion, portal vein invasion, hepatic vein invasion, T2D history and PM of DPYSL3 were the significant risk factors for reduced survival." (PMID 31980687, 2020). "Multivariate analysis further confirmed that hepatic vein invasion, tumour multiplicity (multiple), history of T2D and PM of DPYSL3 remained the significant risk factors for reduced survival." (PMID 31980687, 2020). "In vivo study revealed DPYSL3 knockdown in UC tumours significantly suppressed the growth of tumours and decreased MYC and GLUT1 protein expression." (PMID 37380971, 2023). "The mouse xenograft experiments showed that the growth of tumours derived from BFTC909 cells was hampered after DPYSL3 knockdown." (PMID 37380971, 2023). "The in silico study revealed that DPYSL3 correlated with advanced tumour stage and metastasis development while functioning primarily in the nucleobase-containing compound metabolic process (GO:0006139)." (PMID 37380971, 2023). "Knock down of DPYSL3 expression in UC cell lines decreased tumour invasiveness, suppressed angiogenesis, induced apoptosis, and altered energy metabolic processes." (PMID 37380971, 2023). "A comprehensive study on DPYSL3 interaction with tumour cell energy metabolism will be needed to understand the underlying molecular mechanism." (PMID 37380971, 2023). "DPYSL3 confers tumour aggressiveness by increased cMYC and GLUT1 expression and activation of mTORC1 signalling." (PMID 37380971, 2023). "A metastatic lung tumor model in which the stable DPYSL3 knockdown LLC cells were injected through tail vein was used to analyze the role of DPYSL3 in tumor metastasis in vivo." (PMID 29514686, 2018). "As a proof-of-concept project, this study demonstrated that the saRNA approach is a potent method to enhance the expression of tumor metastasis suppressor DPYSL3 gene, which depends on the sequence specificity of the target gene promoter." (PMID 27014974, 2016). "Dihydropyrimidinase-like 3 (DPYSL3) is a cell adhesion molecule that has been reported to be involved in the metastatic process of tumor cells." (PMID 25096402, 2014). "The prognostic impact of DPYSL3 expression was evaluated in each patients subgroups classified by tumor differentiation." (PMID 25096402, 2014). "The expression of DPYSL3 mRNA was heterogeneous in each GC cell line, and it showed a significant correlation with known tumor promoting factors (VEGF, FAK and EZR)." (PMID 25096402, 2014). "Expression status of DPYSL3 was similar across tumor location (entire, upper third, middle third and lower third)." (PMID 25096402, 2014). "Subsets of these genes (POSTN and DPYSL3) were additionally validated using immunohistochemistry in an independent cohort of follicular thyroid tumors showing a clear gradient pattern from the core to the periphery of the tumor." (PMID 38280140, 2024). "Fresh tumour tissue from 50 patients was used to examine the DPYSL3 mRNA level." (PMID 37380971, 2023). "In addition to modifying UC cell invasiveness, DPYSL3 is involved in diverse molecular processes to promote tumour aggressiveness." (PMID 37380971, 2023). "This leads us to wonder whether DPYSL3 is potential tumor suppressor and m6A methylation may promote tumor progression by reducing their mRNA levels." (PMID 34363020, 2021). "DPYSL3 has been reported to be involved in the metastatic process of tumor cells." (PMID 25096402, 2014). "In addition, decreased DPYSL3 expression in UC cells suppressed tumour angiogenesis." (PMID 37380971, 2023). "Nevertheless, MYCN was found to downregulate DPYSL3, possibly through the action of the enhancer of zeste homolog 2 (EZH2), which methylates histones of tumour suppressor genes." (PMID 38542729, 2024).
tumor (continued). "To confirm the in silico analysis results, we evaluated the relationship between DPYSL3 mRNA expression levels in UBUC and tumour aggressiveness." (PMID 37380971, 2023). "The tumor center was characterized by a higher abundance of LMNA (two proteoforms), dihydropyriminidase-related protein (DPYSL3), tubulin beta (TUBB), myosin light chain 3 (MYL3), and galectin-1 (LGALS1)." (PMID 35512017, 2022). "Methylated genes other than CDK2NA and DPYSL3 may be implicated in an unfavourable prognosis of NBNC-HCC complicated with T2D, particularly because a recent genome-wide study showed PM of several tumour suppresser genes implicated in the tumorigenesis of NBNC-HCC50." (PMID 31980687, 2020). "Although we clearly showed that functional significance of DPYSL3 in PDAC cells, it is possible that the expression of DPYSL3 occurs in tumor stroma cells or connective tissue with some functional relevance in tumor biology." (PMID 24339867, 2013). "However, genes AHCY (adenosylhomocysteinase), DPYSL3 (dihydropyrimidinase like 3), and NME1 (NME/NM23 nucleoside diphosphate kinase 1) are involved in this tumour development." (PMID 38542729, 2024). "Therefore, our study revealed that low expression of FLNA, DPYSL3, KRT5, and TNC promotes tumor migration and development during the pathogenesis of PCa." (PMID 37251946, 2023). "In contrast, TTK increased cell migration and epithelial-to-mesenchymal transition (EMT) by enhancing the expression of dihydropyrimidinase-like 3 (DPYSL3) followed by the increase of snail-regulated EMT, thus reinforce metastatic potential and ultimately tumor metastasis." (PMID 32121246, 2020). "However, regardless of T2D, tumour differentiation was comparable in patients with HCC accompanied by low DPYSL3 expression, corroborating previous findings showing increased capsule infiltration and vascular invasion." (PMID 31980687, 2020). "Taken together, it is conceivable that targeting DPYSL3 gene promoter with our saRNA approach or the TALE-dependent demethylation is feasible to enhance endogenous DPYSL3v2 gene expression, resulting in increased CRMP4a protein levels in vivo and subsequent suppression of tumor metastasis." (PMID 27014974, 2016). "High expression level of DPYSL3 mRNA in GCs was significantly associated with more aggressive phenotype including pT4, invasive growth, lymph node metastasis, positive peritoneal lavage cytology, and UICC stage IV, and but not tumor location." (PMID 25096402, 2014).
infection (1 paper, 2023). The state of being infected such as from the introduction of a foreign agent such as serum, vaccine, antigenic substance or organism. "In the central nervous system, dihydropyrimidinase-like 3 could regulate the inflammatory response of activated immune cells microglia, which respond to infection and inflammation by producing cytokines and phagocytosing cell debris and pathogens." (PMID 37508407, 2023).
DPYSL3 also shares sentences with these, for which no sentence is quoted: autism spectrum disorder (2 papers); metastatic cancer (2); metastatic prostate carcinoma (2); osteosarcoma (2); pancreatic ductal adenocarcinoma (2); acute renal failure (1); Anxiety (1); Astrocytoma (1); Cerebral ischemia (1); cognitive deficits (1); colorectal cancer (1); endometriosis (1); ganglioneuroblastoma (1); glioblastoma (1); Insulin resistance (1); Intellectual disability (1); learning disabilities (1); Myelopathy (1); neurodevelopmental disorder (1); ovarian carcinoma (1); prostate adenocarcinoma (1); renal cell carcinoma (1); rheumatoid arthritis (1); spinal cord injury (1).